RNU6-390P (RNA, U6 small nuclear 390, pseudogene)
Gene: Small nuclear RNA gene on chromosome 5 (157,579,497 to 157,579,599, forward strand). Ensembl gene ENSG00000252068.
Homologues: Orthologues: chimpanzee U6 (100% identical), macaque U6 (93% identical), pig U6 (75% identical), mouse Gm22245 (71% identical), guinea pig U6 (69% identical), rabbit U6 (69% identical). Paralogues in human: RNU6-1060P (82% identical), RNU6-1124P (82% identical), RNU6-1252P (82% identical), RNU6-348P (82% identical), RNU6-41P (82% identical), RNU6-44P (82% identical), RNU6-810P (82% identical), RNU6-1117P (81% identical), RNU6-242P (81% identical), RNU6-29P (81% identical), RNU6-393P (81% identical), RNU6-828P (81% identical), and 1288 more.